IMPA1 (inositol monophosphatase 1)
Description:
Phosphatase involved in the dephosphorylation of myo-inositol monophosphates to generate myo-inositol. Is also able to dephosphorylate scyllo-inositol-phosphate, myo-inositol 1,4-diphosphate, scyllo-inositol-1,3-diphosphate and scyllo-inositol-1,4-diphosphate. Also dephosphorylates in vitro other sugar-phosphates including D-galactose-1-phosphate, glucose-1-phosphate, glucose-6-phosphate, fructose-1-phosphate, beta-glycerophosphate and 2'-AMP. Responsible for the provision of inositol required for synthesis of phosphatidylinositols and polyphosphoinositides, and involved in maintaining normal brain function. Has been implicated as the pharmacological target for lithium (Li(+)) action in brain, which is used to treat bipolar affective disorder. Is equally active with 1D-myo-inositol 1-phosphate, 1D-myo-inositol 3-phosphate and D-galactose 1-phosphate.
Synonyms: IMPA; IMP; MRT59
Tractability: Small molecule: an approved drug acts on it; a structure with a bound ligand is known; it has a high-quality binding pocket; it belongs to a druggable protein family. PROTAC: ubiquitination databases record sites on it; its protein half-life has been measured.
Target class: Enzyme; Hydrolase
Gene: Protein-coding gene on chromosome 8 (81,656,914 to 81,686,848, reverse strand). Ensembl gene ENSG00000133731.
Subcellular location: Cytoplasm
Subcellular location (Human Protein Atlas): Actin filaments; Vesicles
Pathways (Reactome):
Metabolism: Synthesis of IP2, IP, and Ins in the cytosol
Gene Ontology:
Molecular function: fructose-1-phosphatase activity; glucose-1-phosphatase activity; glucose-6-phosphatase activity; glycerol-2-phosphatase activity; identical protein binding; inositol monophosphate 1-phosphatase activity; inositol monophosphate 3-phosphatase activity; inositol monophosphate 4-phosphatase activity; inositol monophosphate phosphatase activity; lithium ion binding; magnesium ion binding; manganese ion binding; protein binding; protein homodimerization activity
Biological process: phosphate-containing compound metabolic process; phosphatidylinositol biosynthetic process; signal transduction; inositol biosynthetic process; phosphatidylinositol phosphate biosynthetic process
Cellular component: cytoplasm; cytosol
Genetic constraint (gnomAD): Loss-of-function variants: 2 observed, 3.86 expected, observed/expected ratio (o/e) 0.52, 90% interval 0.21 to 1.53. That is too few expected variants to judge how well the gene tolerates losing a copy. Missense variants: 49 observed, 62.76 expected, observed/expected ratio (o/e) 0.78, 90% interval 0.62 to 0.99. Synonymous variants: 20 observed, 21.06 expected, observed/expected ratio (o/e) 0.95, 90% interval 0.67 to 1.38.
Homologues: Orthologues: chimpanzee IMPA1 (99% identical), macaque IMPA1 (98% identical), rabbit IMPA1 (91% identical), guinea pig IMPA1 (91% identical), dog IMPA1 (90% identical), mouse Impa1 (86% identical), pig IMPA1 (86% identical), rat Impa1 (85% identical), tropical clawed frog impa1 (79% identical), zebrafish impa1 (67% identical), Drosophila melanogaster CG17026 (36% identical), Drosophila melanogaster CG17027 (35% identical), and 2 more. Paralogues in human: IMPA2 (53% identical), BPNT1 (25% identical), INPP1 (22% identical), BPNT2 (19% identical).
Diseases named in the same sentence as IMPA1 in open-access papers:
IMPA1 is named in the same sentence as 15 diseases in open-access papers, as found by Europe PMC text mining. Sharing a sentence is not in itself a finding about the gene and the disease. The quoted sentences say what the papers report.
bipolar disorder (8 papers, 2017 to 2025). A disorder of the brain that causes unusual shifts in mood, energy, activity levels and the ability to carry out day-to-day tasks. "Previous studies identified lithium as a treatment to treat bipolar disorder which can cause IMPA1 KO features in mRNA level." (PMID 35796646, 2023). "Importantly, IMPA1 is one of the targets of lithium in neurons and has been implicated in the pathogenesis of bipolar disorders." (PMID 33626357, 2021). "This study demonstrates that lithium that is used to treat bipolar disorder acts via IMPA1 to regulate calcium signalling and neuronal excitability." (PMID 38056909, 2024). "The general interest in IMPA1 function has steadily risen over the years since it was discovered that this enzyme is suppressed by lithium, a potent mood stabilizer used to treat bipolar disorder, a psychiatric ailment with a high global prevalence." (PMID 37508980, 2023). "Lithium, which is largely used for bipolar disorder treatment, in high concentrations inhibits the enzyme IMPA1 in a non-competitive way." (PMID 37508980, 2023). "Despite the higher frequency of psychiatric symptoms in MRT59 patients, bipolar disorder has been associated with changes in IMPA2 and not in IMPA1." (PMID 37508980, 2023). "In contrast, bipolar disorder, which was significant in the UK GWAS dataset, was also significantly present in the merged set by adding two novel genes from the Japanese GWAS: DNAH8 (chr6:38,681,087-39,000,568) and IMPA1 (chr8:82,567,151-82,600,589)." (PMID 36902448, 2023).
Intellectual disability (4 papers, 2018 to 2025). "Intellectual disability associated with IMPA1 (MRT59) was initially described in a large consanguineous family from the hinterlands of Northeast Brazil." (PMID 37508980, 2023). "This is the first study to investigate those two variables in patients with IMPA1-associated intellectual disability." (PMID 37508980, 2023). "Induced pluripotent stem cells (IPSC) technology to model IMPA1 intellectual disability was used and identified that pathogenic variants affect the ability of neural progenitor stem cells to differentiate into neurons but not into astrocytes." (PMID 37508980, 2023). "A homozygous loss-of-function variant in IMPA1 was initially described in nine individuals with severe intellectual deficiency belonging to a large consanguineous family of the hinterlands of Northeast Brazil." (PMID 37508980, 2023). "Our group conducted a previous study to evaluate the neurophysiologic mechanisms that mediate the IMPA1-associated intellectual disability phenotype." (PMID 37508980, 2023). "A homozygous frameshift mutation in IMPA1, coding for the enzyme inositol monophosphatase 1 (IMPase), has recently been associated with severe intellectual disability (ID) in a geographically isolated consanguineous family in Northeastern Brazil." (PMID 30616629, 2019). "A homozygous frameshift mutation in the gene coding for the enzyme inositol monophosphatase 1 (IMPA1) has recently been associated with severe intellectual disability (ID) in a geographically isolated consanguineous family in Northeastern Brazil." (PMID 30616629, 2019). "Regarding the ICD-10 (classification of severity based on IQs), our results (IQs ranged from 40 to 44) revealed moderated intellectual disability in all IMPA1 patients." (PMID 37508980, 2023).
breast carcinoma (2 papers, 2023 to 2025). "Results showed that CNV of IMPA1 was significantly higher in breast cancer and was closely related to its mRNA level, but few mutations were identified in IMPA1." (PMID 35796646, 2023). "High IMPA1 status was significantly associated with a worse breast cancer prognosis." (PMID 35796646, 2023). "Moreover, an integrated database named Gene Set Cancer Analysis (GSCA) that was used for genomic gene set cancer analysis was adopted for further analyzing and obtaining more genomic information about IMPA1 in breast cancer." (PMID 35796646, 2023). "In addition, although methylation of IMPA1 was associated with its mRNA level, it was not significantly altered in breast cancer compared with normal control." (PMID 35796646, 2023). "Therefore, we used those five target genes and IMPA1 as a gene set to investigate genomic variations by gene set variable analysis (GSVA) of breast cancer, and found that it was significantly higher in breast cancer, especially in TNBC, and significantly correlated with cell‐cycle pathway activity." (PMID 35796646, 2023).
cervical cancer (1 paper, 2023). A primary or metastatic malignant neoplasm involving the cervix. "IMPA2 is an important paralog of IMPA1 and plays an oncogenic role in cervical cancer." (PMID 35796646, 2023).
diabetes (1 paper, 2024). "IMPA1 is an enzyme responsible for inositol synthesis; deficiency in IMPA1 leads to a decline in inositol and mitochondrial fission, ultimately leading to the development of diabetes and mitochondrial diseases." (PMID 39553470, 2024). "As a result, IMPA1 was found to be significantly downregulated in the diabetes group in databases GSE15932, GSE15653, and GSE166467." (PMID 39553470, 2024).
gestational diabetes (1 paper, 2024). Carbohydrate intolerance first diagnosed during pregnancy. "Recently, a case-control study demonstrated that in gestational diabetes, higher maternal glycemia is associated with decreased protein and mRNA expression levels of IMPA1." (PMID 39553470, 2024).
cancer (5 papers, 2021 to 2025). A tumor composed of atypical neoplastic, often pleomorphic cells that invade other tissues. "However, IMPA1 expression profiles and its associated functional role in cancer progression, especially in TNBC, remain unexplored." (PMID 35796646, 2023). "While inositol monophosphatases have been extensively studied in neuropsychiatric disorders, emerging evidence has further linked IMPA1 and IMPA2 to the pathogenesis of various cancers." (PMID 41032702, 2025). "By analyzing the proteomic data of 90 TNBC patients from our cancer center, we found inositol monophosphatase 1 (IMPA1) was upregulated in TNBC tissues compared to normal controls, but its functional role in TNBC progression has not been reported yet." (PMID 35796646, 2023). "By reanalyzing the quantitative proteomic data of TNBC samples in Shanghai cancer center, we found IMPA1 was upregulated in TNBC tumor tissues." (PMID 35796646, 2023).
tumor (5 papers, 2021 to 2025). "Although many previous reports imply the association between IMPA1 and brain disfunctions, there is no study of IMPA1 as tumor‐associated promotor." (PMID 35796646, 2023). "Here, we found that IMPA1 increased TNBC cell proliferation and migration capacity, and promoted xenograft tumor growth and metastasis." (PMID 35796646, 2023). "In cSCC versus AK, IMPA1 was the sole SMG to be significantly differentially expressed in at least two datasets, being upregulated in cSCC, suggesting a tumor promoter role." (PMID 33482222, 2021). "In this study, we revealed for the first time that IMPA1 was upregulated in TNBC cell lines and tumor tissues, and exerted an oncogenic role in TNBC growth and metastasis through upregulating five downstream targets and their associated mTOR pathway and EMT process." (PMID 35796646, 2023).
infection (1 paper, 2023). The state of being infected such as from the introduction of a foreign agent such as serum, vaccine, antigenic substance or organism. "To investigate the biological function of IMPA1 in TNBC, we generated stable SUM159PT and BT549 cell lines overexpressing HA‐IMPA1 by infection of lentiviral vectors." (PMID 35796646, 2023).
IMPA1 also shares sentences with these, for which no sentence is quoted: Heat Stroke (1 paper); lymphoma (1); mitochondrial disease (1); Neurological Disorder (1); Parkinson disease (1); psychosis (1).